PEMT (phosphatidylethanolamine N-methyltransferase)
Diseases named in the same sentence as PEMT in open-access papers (continued):
Sharing a sentence is not in itself a finding about the gene and the disease.
cancer (17 papers, 2014 to 2025). A tumor composed of atypical neoplastic, often pleomorphic cells that invade other tissues. "Higher PEMT activity may be associated with breast and liver tumors’ aggressiveness due to its role in lipid metabolism necessary for highly proliferating cancer cells." (PMID 36613653, 2022). "The waterfall plots further visualized the mutation types of CHKB and PEMT in pan-cancer." (PMID 36451813, 2022). "In addition, we hypothesized that PEMT rs7946 may disturb the concentrations of choline-related metabolites and, thus, influence risk of cancer in corresponding genotype carriers." (PMID 38351975, 2024). "However, a previous study found that the polymorphism of PEMT rs7946 is associated with changed enzyme activity, thus the association between this variant and cancer risk may be mediated by disturbed choline metabolism." (PMID 38351975, 2024). "As both enzymes are molecular targets for cancer therapy, with specific inhibitors of FASN activity or by inducing LPL activity in non-cancer tissues by peroxisome proliferator-activated receptor γ agonists, PEMT may also be a promising diagnostic and therapeutic target." (PMID 24932311, 2014). "PEMT is then involved in the synthesis of PC from PE, as cancer cells are characterized by increased growth and synthesis of new cell membranes has high requirements for PC." (PMID 24932311, 2014). "It contains 10 genes with correlated expression level change, including four with prior association with cancer (NCOR1, FLCN, PEMT and PTRH2)." (PMID 24670534, 2014). "Moreover, SHHZF also increased the activity of phosphatidylethanolamine N-methyltransferase (PEMT), a liver-specific enzyme that negatively regulates cancer cell proliferation, and suppressed the abnormal metabolism of bile acid." (PMID 35185591, 2022). "PEMT activity was decreased in cancers, which might lead to lower levels of polyunsaturated PCs." (PMID 29190918, 2017). "Thus, PEMT involvement in cancer requires further evaluation." (PMID 24932311, 2014). "Additional genes with significance or significant trends for Cancer/control group differences included FCN1 and PEMT at the intron region." (PMID 29876008, 2018). "For all other enzymes discussed in this review, a lot more basic and translational research is required to evaluate the exact molecular roles of PtdCho-PLC, SMases, choline transporters, GDEs, PEMT, and ETKN in cancer." (PMID 28083512, 2016). "PEMT expression in the cancer tissues was equal to its expression in the adjacent non-cancer tissues and did not correlate with the disease stage (results not shown)." (PMID 24932311, 2014). "Irrespective of cancer status, several SNPs were found to be associated with altered serum folate concentrations, including the D919G SNP in methionine synthase (MTR), the L474F SNP in serine hydroxymethyl transferase 1 (SHMT1) and the V175M SNP in phosphatidyl ethanolamine methyltransferase (PEMT)." (PMID 29474406, 2018). "In conclusion, increased PEMT expression in NSCLC tissues (relative to the adjacent non-cancer lung tissue) predicts shorter patient survival, independently of increased FASN or LPL activities in the same cancer tissues." (PMID 24932311, 2014).
infection (4 papers, 2014 to 2024). The state of being infected such as from the introduction of a foreign agent such as serum, vaccine, antigenic substance or organism. "Subsequent to infection, S. enterica’s insult to estrogen would attenuate the transcription of PEMT mRNA in hepatocytes, thus indirectly attenuating the synthesis of PC." (PMID 39590326, 2024). "The expression of PEMT mRNA was similar in patients with HCV genotype 1 and HBV but was significantly higher in patients with HCV-genotype 3 infection compared to either HCV genotype 1 (p < 0.01) or HBV (p < 0.05)." (PMID 37240132, 2023). "Thus, we investigated whether the infection of HBV affects PC biosynthesis known to be regulated by 2 pathways: the CDP-choline and phosphatidylethanolamine N-methyltransferase (PEMT) pathways." (PMID 25101682, 2014).
Metabolic Disorders (3 papers, 2016 to 2023). "In summary, our data suggest that PEMT plays a role in regulating FD and has implications in metabolic diseases." (PMID 38069170, 2023). "Furthermore, the increased expression of vis PEMT is related to the progression of metabolic diseases (T2D and NASH)." (PMID 38069170, 2023).
cardiovascular diseases (1 paper, 2023). "Further investigations have indicated that the PEMT locus of this transcript is related to the progression of multiple cardiovascular diseases." (PMID 37191416, 2023).
digestive system cancer (1 paper, 2024). A primary or metastatic malignant neoplasm involving any part of the digestive system. "Stratified analyses were performed to assess the association between PEMT rs7946 and digestive system cancer risk in various subgroups." (PMID 38351975, 2024). "Although we failed to confirm any mediating role of choline and betaine, we proved that the choline-to-betaine ratio partially mediated the association of PEMT rs7946 with digestive system cancer risk in this population." (PMID 38351975, 2024). "In conclusion, this study provides evidence that supports a significant association between PEMT rs7946 and digestive system cancer risk, especially in individuals with a lower choline-to-betaine ratio." (PMID 38351975, 2024). "We aimed to investigate the potential association between PEMT rs7946 and digestive system cancer risk and to explore possible effect modifiers and potential mediating effects from choline-related metabolites." (PMID 38351975, 2024). "A substantially higher risk of digestive system cancer was seen for those with the CC genotypes (adjusted OR: 1.31; 95% CI: 1.04, 1.66; P = 0.023) of PEMT rs7946 in the conditional logistic regression model." (PMID 38351975, 2024). "Specifically, the result of the mediation analysis indicated that the choline-to-betaine ratio significantly mediated 13.55% of the association between PEMT rs7946 and digestive system cancer (P = 0.018)." (PMID 38351975, 2024). "To assess the association of PEMT rs7946 and digestive system cancer, we estimated odds ratios with 95% confidence intervals (CIs) using conditional logistic regression." (PMID 38351975, 2024). "Stratified analyses were performed to assess the association of PEMT rs7946 with risk of digestive system cancer in various subgroups." (PMID 38351975, 2024). "Our results also suggest that the choline-to-betaine ratio may partially mediate the association between PEMT rs7946 and digestive system cancer risk." (PMID 38351975, 2024). "Given the significant association and the theoretical causality between the PEMT rs7946 and digestive system cancer, we hypothesized that this relationship may be mediated by the concentrations of choline-related metabolites." (PMID 38351975, 2024). "Our study suggested that PEMT rs7946 may affect risk of digestive system cancer through direct and indirect pathways, and the choline-to-betaine ratio may partially mediate the indirect effect." (PMID 38351975, 2024). "Furthermore, the mediation analysis indicated that the choline-to-betaine ratio played a significant role in mediating 13.55% of the association between PEMT rs7946 and digestive system cancer (P = 0.018)." (PMID 38351975, 2024). "First, because data about pathologic character were lacking, we were unable to evaluate the relationship between PEMT rs7946 and subtypes of different digestive system cancers." (PMID 38351975, 2024). "We aimed to investigate the relationship between PEMT rs7946 and digestive system cancer and examine possible effect modifiers and mediators." (PMID 38351975, 2024).
kidney disease (1 paper, 2020). "A deeper understanding of the role and the mechanism of pEMT may help in developing novel therapies to prevent and halt fibrosis in kidney disease." (PMID 33041867, 2020).
PEMT also shares sentences with these, for which no sentence is quoted: type 2 diabetes (3 papers); coronary artery disease (2); Hyperglycemia (2); Infertility (2); ischemic stroke (2); Kidney (2); overnutrition (2); abetalipoproteinemia (1); adenocarcinoma (1); alcohol abuse (1); Alzheimer disease (1); autoimmune hepatitis (1); Autoimmune Thyroiditis (1); cholangiocellular carcinoma (1); chronic hepatitis B (1); chronic hepatitis C (1); Cirrhosis (1); cystic fibrosis (1); Down syndrome (1); glioma (1); Glucose intolerance (1); hepatitis C (1); hyperlipidemia (1); inherited diseases (1); liver (1); mantle cell lymphoma (1); neural tube defect (1); Parkinson disease (1); Pheochromocytoma and Paraganglioma (1); prediabetes (1).